RCAN1 (regulator of calcineurin 1)
Diseases named in the same sentence as RCAN1 in open-access papers (continued):
Sharing a sentence is not in itself a finding about the gene and the disease.
brain ischemia (4 papers, 2012 to 2020). Diminished or absent blood supply to the brain caused by obstruction (thrombosis or embolism) of an artery resulting in neurologic damage. "Rcan1 is also associated with oxidative stress, which together with its sensitivity to calcium suggests a possible implication in brain ischemia." (PMID 22397398, 2012). "RCAN1 functions in the immune response, angiogenesis, cardiac remodeling, and brain ischemia/reperfusion injury." (PMID 32589657, 2020). "Using a different focal brain ischemia model, a recent report showed upregulation of Rcan1 protein in both the neural and glial compartments around the infarcted area." (PMID 22397398, 2012). "Brain ischemia/reperfusion (I/R) injury in vivo increased mRNA and protein expression of the calcium-inducible Rcan1 isoform (Rcan1-4)." (PMID 22397398, 2012). "In the present work, we investigate the role of Rcan1 protein in response to brain ischemia." (PMID 22397398, 2012). "Recent evidence indicates that Rcan1 is upregulated around the infarct area after experimental stroke; however, the role of Rcan1 in the response to brain ischemia and calcium overload is unknown." (PMID 22397398, 2012).
glioma (4 papers, 2017 to 2026). A benign or malignant brain and spinal cord tumor that arises from glial cells (astrocytes, oligodendrocytes, ependymal cells). "Bioinformatic analysis revealed that 44.2% of these HLA-I alleles, spanning 92.4% of glioma patients, potentially presented a variety of different peptides encompassing RCAN1-4 SJe4/e5." (PMID 41436600, 2026). "We showed that RCAN1-4 was the predominant isoform associated with glioma aggressiveness and the most abundant RCAN1 transcript in GBM." (PMID 41436600, 2026). "Our study implicated a novel therapeutic approach for glioma by RCAN1 through inhibition of NF-κB signaling." (PMID 28061453, 2017). "In summary, our data suggest that NFATc3 is highly expressed in human glioma and silencing of this member is critical for RCAN1-4 expression in U251." (PMID 31249342, 2019). "Our study here identified RCAN1 can suppress glioma growth as an inhibitor of NF-κB signaling pathway." (PMID 28061453, 2017). "To investigate if RCAN1 suppresses glioma viability by inhibiting NF-κB signaling pathway, we infected T98G cells by lentivirus expressing RCAN1 for 72hrs." (PMID 28061453, 2017). "So we want to explicit if RCAN1 can suppress the growth of glioma and becomes a new therapeutic target." (PMID 28061453, 2017). "Our studies provided a potential therapeutic pathway for glioma by overexpressing RCAN1 to inhibit NF-κB signaling." (PMID 28061453, 2017). "And RCAN1 overexpression exacerbated the glioma cell apoptosis after TNFα treatment (p < 0.005, lane 3 versus lane 4)." (PMID 28061453, 2017). "In the present study, we have solid data to show that RCAN1 can inhibit the nuclear translocation of NF-κB protein then affect the activity of NF-κB signaling pathway in glioma cells." (PMID 28061453, 2017). "Meanwhile, we confirmed RCAN1 expression can inhibit NF-κB signaling pathway in glioma cells by attenuating NF-κB protein nuclear translocation, and resulted in suppressing the growth of glioma cells." (PMID 28061453, 2017). "RCAN1 knockdown dramatically activated NF-κB signaling pathway and promoted the viability of glioma cells." (PMID 28061453, 2017). "Therefore, we investigated the HLA-I landscape of adult and pediatric glioma cohorts to identify putative MHC-I-presenting RCAN1-4 SJe4/e5 epitopes." (PMID 41436600, 2026). "Notably, in addition to RCAN1-4, the canonical RCAN1 isoform in the brain, RCAN1-1, is also expressed in glioma patients." (PMID 41436600, 2026). "Similarly, RCAN1 suppressed viability of glioma cells and induced glioma cell apoptosis by inhibiting the NF-κB pathway." (PMID 35717152, 2022). "And knockdown expression of RCAN1 could activate NF-κB signaling and promote the growth of glioma cells, clearly indicating that RCAN1 can inhibit the transcriptional activity of NF-κB to suppress the growth of glioma cells." (PMID 28061453, 2017). "TUNEL staining was performed in glioma cells infected with lentivirus expressing RCAN1." (PMID 28061453, 2017). "RCAN1 inhibited NF-κB signaling activity in human glioma cells." (PMID 28061453, 2017). "We are interested to know if RCAN1 can affect NF-κB signaling and subsequent glioma tumorigenesis." (PMID 28061453, 2017). "Overexpression of RCAN1 markedly suppressed glioma cells’ viability and increased apoptosis." (PMID 28061453, 2017). "Overexpression of RCAN1 markedly reduced glioma cells viability." (PMID 28061453, 2017). "Both C/EBPβ and RCAN1-4 are highly expressed in GBM and glioma stem cells as mesenchymal subtype hallmarks." (PMID 41436600, 2026). "In higher-grade gliomas (i.e., GBM, IDH-WT, and pediatric HGG), RCAN1-4 was the predominant RCAN1 isoform, with its expression level increasing with tumor grade." (PMID 41436600, 2026). "Therefore, RCAN1 could be a novel and valuable anti-glioma target." (PMID 28061453, 2017).
glioma (continued). "Thus, we next assessed the protein expression of the RCAN1 isoforms and detected high RCAN1-4 expression across multiple mesenchymal GBM cell lines and glioma stem cell (GSC) lines." (PMID 41436600, 2026). "Since MTT assay showed RCAN1 decreased cell viability without affecting cell proliferation, we examined if RCAN1 affected glioma cell apoptosis." (PMID 28061453, 2017). "Taken together, our data showed that RCAN1 overexpression can suppress glioma cells viability through inducing apoptosis rather than arrest of cell cycle." (PMID 28061453, 2017). "The results showed that overexpression of RCAN1 do not have an important role in the proliferation of glioma cells (p>0.05)." (PMID 28061453, 2017).
Hypertension (4 papers, 2018 to 2021). The presence of chronic increased pressure in the systemic arterial system. "Surprisingly, conditional Rcan1 deletion in either vascular cell-type induces a hypercontractile phenotype and aortic medial layer disorganization, predisposing to hypertension-mediated aortic rupture, IMH, and aneurysm." (PMID 30442942, 2018). "Moreover, the conditional deletion of Rcan1 in smooth muscle cells (SMCs) or endothelial cells (ECs) disrupts aortic wall homeostasis, predisposing the aorta to hypertension-induced IMH, and subsequent aneurysm and rupture." (PMID 33267791, 2020). "However, we show here that the inducible deletion of Rcan1 in SMCs or endothelial cells (ECs) disrupts aortic wall homeostasis, predisposing the aorta to hypertension-induced rupture, IMH, and aneurysm." (PMID 30442942, 2018). "Here the authors show that tissue-specific inducible deletion of Rcan1 in vascular cell types predisposes to hypertension-mediated aortic rupture, intramural hematoma, and aneurysm, due to increased GSK-3b-mediated activation of ROCK and induction of a hypercontractile phenotype." (PMID 30442942, 2018). "As NPPA has been demonstrated to inhibit NFAT activation, this DS‐induced up‐regulation of NPPA could explain why RCAN1 was not up‐regulated in DS‐treated rats, even though crucial Ca2+‐handling genes (ATP1A2, SERCA2A and PLN) were dysregulated upon DS‐induced hypertension." (PMID 31368189, 2019).
lymphoma (4 papers, 2015 to 2023). A malignant (clonal) proliferation of B- lymphocytes or T- lymphocytes which involves the lymph nodes, bone marrow and/or extranodal sites. "Our study implicated a novel therapeutic approach for lymphoma by RCAN1 through inhibition of NF-κB signaling." (PMID 26492364, 2015). "RCAN1 resulted in a decrease in the cell viability of lymphoma Raji cells and inhibited the growth of lymphoma transplants in mice by inhibiting NF-κB." (PMID 35717152, 2022). "Our recent reports showed that NF-κB signaling regulated RCAN1 isoform 4 gene transcription through a NF-κB responsive element and RCAN1 as a novel inhibitor of NF-κB signaling pathway can suppress lymphoma growth in mice." (PMID 28061453, 2017). "Previously we identified regulator of calcineurin 1 (RCAN1) as an endogenous inhibitor of NF-κB signaling pathway in lymphoma." (PMID 28061453, 2017). "Overexpression of RCAN1 by adenovirus reduced cell viability in lymphoma Raji cells and restrained the growth of lymphoma transplants in mice." (PMID 26492364, 2015). "We further found that N terminus 1–103aa of RCAN1 is sufficient to inhibit NF-κB and reduce cell viability of lymphoma cells." (PMID 26492364, 2015). "Our studies provided a novel therapeutic pathway for lymphoma by activating RCAN1 to inhibit NF-κB signaling." (PMID 26492364, 2015). "Overexpression of RCAN1 by adenovirus in vitro markedly reduced lymphoma Raji cell viability via activation of caspases." (PMID 26492364, 2015). "The results indicated that RCAN1 reduced the incidence, as well as the growth of lymphoma xenografts in mice." (PMID 26492364, 2015). "Previously, we showed RCAN1 inhibited NF-κB signaling in lymphoma." (PMID 28061453, 2017). "And RCAN1 expression in vivo reduced tumor growth in xenografted lymphomas in SCID mice." (PMID 26492364, 2015). "Overexpression of RCAN1 could restrain the lymphoma growth in mice via inhibiting NF-κB7." (PMID 37576400, 2023). "In addition, overexpression of RCAN1 could reduce cell viability in lymphoma Raji cells and restrain the lymphoma growth in mice." (PMID 37576400, 2023).
anaphylaxis (3 papers, 2017 to 2025). An acute hypersensitivity reaction that occurs from exposure to an allergen. "It was found that endothelial Rcan1 is increased in response to anaphylaxis as a mechanism of strengthening the endothelium and mice who were Rcan-1 deficient had a more severe response to histamine." (PMID 41016999, 2025). "Previous studies using experimental anaphylaxis in Rcan1-deficient mice have found a role for Rcan1 in regulating Fc-εRI-mediated signaling and mast-cell function." (PMID 29104573, 2017). "Moreover, we studied the permeability effects of Rcan1 causing either endothelial barrier rupture or strengthening in response to mediators of anaphylaxis and also analyzed the plausible endothelial mechanisms exerting these functions." (PMID 29104573, 2017). "We have previously demonstrated that two different endothelial molecules (Regulator of calcineurin 1 and Fibroblast growth factor–inducible molecule 14) participate in the regulation of the endothelial barrier function related with anaphylaxis." (PMID 34248989, 2021). "Our results in human ECs and an experimental mice model support the immunosuppressive function of Rcan1 for vascular permeability and anaphylaxis." (PMID 29104573, 2017). "This study evaluates Rcan1 expression in human ECs in response to mediators of anaphylaxis and, more specifically, the involvement of histamine receptors involved in Rcan1 expression." (PMID 29104573, 2017). "Given the crucial role exerted by mediators on the vascular wall in anaphylaxis, we assessed the impact of anaphylaxis on Rcan1 expression in human ECs, as well as its functional involvement in vascular permeability and cell dilation." (PMID 29104573, 2017). "In summary, this work contributes to the knowledge of anaphylaxis, showing endothelial Rcan1 as an inducible molecule which is modulated in the endothelial compartment upon contact with histamine through a calcineurin-sensitive pathway." (PMID 29104573, 2017). "Using three experimental designs simulating different degrees of allergic sensitivity, we looked for Rcan1 expression in target organs in mice undergoing anaphylaxis." (PMID 29104573, 2017). "Although RhoA and ROCK have been recently recognized as key targets mediating histamine-induced vascular leakage and anaphylactic shock, our results do not reveal significant differences in MLCK/ROCK1 when Rcan1 is overexpressed in HV-ECs." (PMID 29104573, 2017).
aneurysm (3 papers, 2013 to 2021). Bulging or ballooning in an area of an artery secondary to arterial wall weakening. "To determine the development of IMH in Rcan1-deficient mice, we used ultrasound imaging to monitor for the presence of aneurysms in the aortas of mice treated with AngII for 28 days." (PMID 30442942, 2018). "Constitutive deletion of Rcan1 has been previously shown to prevent Angiotensin II-induced aneurysm in mice." (PMID 30442942, 2018). "Here we generate mice conditionally lacking each isoform or all isoforms in vascular smooth muscle cells, endothelial cells, or ubiquitously, to determine the contribution to aneurysm development of Rcan1 isoforms in vascular cells." (PMID 30442942, 2018). "Our previous studies in constitutive Rcan1−/− mice showed that Rcan1 is a critical mediator of neointima formation, aneurysm, and atherosclerosis." (PMID 30442942, 2018). "We have previously shown that constitutive deletion of Rcan1 isoforms prevents Angiotensin II-induced aneurysm in mice." (PMID 30442942, 2018). "Rcan1 plays a critical role in vascular wall remodelling associated with aneurysm and neointima formation after angioplasty; and notably, BM transplantation experiments showed that haematopoietic-cell expression of Rcan1 is not required for aneurysm." (PMID 24127415, 2013).
glioblastoma (3 papers, 2007 to 2026). The most malignant astrocytic tumor (WHO grade IV). "However, in lymphoid neoplasm diffuse large B-cell lymphoma (DLBC), glioblastoma multiforme (GBM), pancreatic adenocarcinoma (PAAD), skin cutaneous melanoma (SKCM), and thymoma (THYM), RCAN1 expression in tumor samples is higher than that in normal samples." (PMID 35717152, 2022).
leukemia (3 papers, 2007 to 2013). A malignant (clonal) hematologic disorder, involving hematopoietic stem cells and characterized by the presence of primitive or atypical myeloid or lymphoid cells in the bone marrow and the blood. "Microarray analysis has correlated specific upregulation of RCAN1 with GC-dependent growth arrest and apoptosis of leukemic T lymphoblasts and apoptosis of pre B-leukemia cells." (PMID 19725972, 2009).
memory impairment (3 papers, 2011 to 2025). "In a previous study, we found AD-like hippocampal mitochondrial dysfunction, oxidative stress, synaptic plasticity failure, and memory impairments in aged, but not young, RCAN1 TG mice." (PMID 35610565, 2022).
myocardial infarction (3 papers, 2016 to 2020). Gross necrosis of the myocardium, as a result of interruption of the blood supply to the area, as in coronary thrombosis. "The protective effect of RCAN1 on I/R injury is partially mediated by inhibiting calcineurin activity, which is further supported by that FK506, a calcineurin inhibitor, confers protection to myocardial infarction in Rcan1 KO mice." (PMID 33267791, 2020).
myocardial ischemia (3 papers, 2020 to 2023). A disorder of cardiac function caused by insufficient blood flow to the muscle tissue of the heart. "In addition, RCAN1 contributes to the maintenance of mitochondrial function and modulates tissue damage during myocardial ischemia-reperfusion." (PMID 37063972, 2023).
Nephropathy (3 papers, 2021 to 2023). A nonspecific term referring to disease or damage of the kidneys. "Aberrant expression of the regulator of calcineurin 1 (RCAN1), recognized as an endogenous inhibitor of the calcineurin phosphatase, has been shown to be extensively involved in various kidney diseases." (PMID 37507403, 2023).
neuroblastoma (3 papers, 2014 to 2025). Neuroblastoma (NB) is the most common solid, extracranial childhood tumor. "In the case of neuroblastoma, decreased risk has been attributed to overexpression of chromosome 21 genes such as DYRK1A and RCAN1 (formerly known as DSCR1)." (PMID 40333415, 2025). "In this study, we use human neuroblastoma SH‐SY5Y cells stably expressing RCAN1.1S and rat primary neurons infected with RCAN1.1S expression lentivirus to study the association of RCAN1 with mitochondrial functions." (PMID 27861892, 2017).
oral squamous cell carcinoma (3 papers, 2021 to 2023). "In addition, miR-103a-3p was reported to regulate proliferation and apoptosis by targeting RCAN1 in oral squamous cell carcinoma (OSCC) cell lines." (PMID 36273122, 2022). "Moreover, miR-103a-3p regulates proliferation and apoptosis by targeting RCAN1 in oral squamous cell carcinoma (OSCC) cells, miR-103 promotes HCC growth by inhibiting AKAP12 or by promoting glucose metabolism function, and miR-103 promotes metastasis and EMT by inhibiting LATS2." (PMID 36273122, 2022).
Stroke (3 papers, 2012 to 2020). Sudden impairment of blood flow to a part of the brain due to occlusion or rupture of an artery to the brain. "Our results support a protective role for Rcan1 during the inflammatory response to stroke, and underline the importance of the glial compartment in the inflammatory reaction that takes place after ischemia." (PMID 22397398, 2012). "We report that Rcan1-4 protein and mRNA accumulate in brain cortex early after ischemia/reperfusion, mainly in glial fibrillary acidic protein (GFAP)-positive cells, and that Rcan1 deficiency worsens stroke outcome and increases expression of inflammation-associated genes." (PMID 22397398, 2012). "To assess the role of Rcan1 after stroke, we measured infarct volume after 48 h of reperfusion in Rcan1 knockout (KO) and wild-type (WT) mice." (PMID 22397398, 2012). "The putative transcription factor HIF-1 binding site within the RCAN1 promoter region may mediate the alteration of RCAN1 expression under hypoxia, ischemia, and stroke conditions, promoting AD development." (PMID 32566665, 2020). "We next analyzed the functional consequence of Rcan1 deletion in this stroke model." (PMID 22397398, 2012). "Our data support a protective role for Rcan1 during the inflammatory response to stroke." (PMID 22397398, 2012).
cognitive decline (2 papers, 2022 to 2025). "More generally, perturbation of rest-activity profiles stemming from increased RCAN1 levels in normatively aging individuals may contribute to aging-associated cognitive decline." (PMID 35610565, 2022). "Additionally, RCAN1 (regulator of calcineurin 1) may influence neurodegeneration pathways, further complicating the genetic landscape affecting cognitive decline in this population." (PMID 40748434, 2025). "Given that RCAN1 levels are elevated in the brains of DS, AD, and normally aging individuals, aberrant RCAN1 signaling may disrupt circadian clock function and, in turn, promote cognitive decline and AD-related neurodegeneration." (PMID 35610565, 2022).
colon cancer (2 papers, 2021 to 2022). "In colon cancer cell lines, RCAN1 suppressed tumor growth and metastasis by inhibiting the CN-NFAT signaling pathway." (PMID 35717152, 2022). "In CRC, RCAN1 is regarded as a biomarker to predict recurrence in stages II and III of colon cancer." (PMID 35717152, 2022). "RCAN1, an obesity-related gene, was regarded as a biomarker for predicting recurrence in stages II and III of colon cancer." (PMID 35717152, 2022).
dementia (2 papers, 2019 to 2022). Loss of intellectual abilities interfering with an individual's social and occupational functions. "In conclusion, our data demonstrate that RCAN1 is differentially regulated between the peripheral and central compartments in AD and should be further investigated to understand its potential role in dementia of AD and DLB." (PMID 31263630, 2019). "Similarly, previous studies have shown that the level of RCAN1 mRNA was increased in the AD brain and that the level of RCAN1 protein was increased in the pyramidal neurons of the AD temporal lobe, but there is almost nothing in the literature about the levels of RCAN1 in other types of dementia." (PMID 31263630, 2019). "Not only the APP gene is responsible for dementia in DS, GATD3A, SOD1, ERG, BACE2, DSCR1/RCAN1, APOE (19q13.32), BACE1 (11q23.3), IL1B (2q14.1), GSAP (7q11.23), UBB (17p11.2), and IRS1 (2q36.3) genes may also play a major role in dementia in DS." (PMID 35676933, 2022).